HLA-DRB1 (major histocompatibility complex, class II, DR beta 1)
Diseases named in the same sentence as HLA-DRB1 in open-access papers (continued):
Sharing a sentence is not in itself a finding about the gene and the disease.
sarcoidosis (continued). "To detect variants predisposing to sarcoidosis and to identify genetic differences between patient subgroups, we studied four genes in the MHC Class III region (LTA, TNF, AGER, BTNL2) and HLA-DRA with tag-SNPs and their relation to HLA-DRB1 alleles." (PMID 28469621, 2017). "In Japan, the HLA-DRB1*03 allele is rare, explaining the non-association of the variant with sarcoidosis." (PMID 28469621, 2017). "The etiology of sarcoidosis is still obscure; however, sarcoidosis is thought to be triggered by either infectious agents or exposure to environmental substances in patients with various genetic factors, such as the HLA-DRB1 gene." (PMID 29123243, 2017). "In addition there was a significant difference in the frequency of the HLA-DRB1 *12 allele between pulmonary (1%) and EPS patients (8.2%, p < 0.05) and this allele was also identified as a risk factor for sarcoidosis." (PMID 25866481, 2015). "In that study, subsequent conditional analyses revealed four additional independent variants (SNPs rs146146117 HLA-DQA1, rs9461776 HLA-DRB1, rs715299 NOTCH4, and rs9272320 HLA-DQA1) associated with sarcoidosis risk in the HLA class II region at the suggestive GWA significance threshold." (PMID 24663488, 2014). "Additional studies have revealed a strong association between HLA-DRB1*0301 and remarkable expansions of CD4+ T cells expressing T-cell receptors using the AV2S3 gene segment in bronchoalveolar lavage fluid (BALF) of Scandinavian sarcoidosis patients." (PMID 19480659, 2009). "In summary, we used WES to further characterize genetic differences between persistent and resolved sarcoidosis patients and to test the hypothesis whether different variations are associated in relation to the class II markers (HLA-DRB1*03:01/HLA-DRB1*04:01-DPB1*04:01)." (PMID 31921204, 2019). "HLA-DRB1*01 and DRB1*04 were found to have protective effects against sarcoidosis in Caucasian populations, whilst HLA-DRB1*03, DRB1*11, DRB1*12, DRB1*14, and DRB1*15 were identified as risk factors for the disease." (PMID 40078389, 2025). "The mycobacterial catalase-peroxidase protein (mKatG) has been detected in a majority of sarcoidosis samples and is reported to preferentially elicit a response from TCR AV2S3 + T cells in the lungs of HLA-DRB1*03 + patients." (PMID 39904950, 2025). "These authors also showed that antigen presenting cells expressing HLA-DRB1 * 1101 interact with mycobacterial peptides, ESAT-6 and katG, to elicit a TH1 polarized response from sarcoidosis T-cells." (PMID 37110254, 2023). "In Finnish sarcoidosis patients, certain HLA markers (HLA-DRB1*03:01, HLA-DRB1*04:01-DQB1*04:01) have been shown to be more common in patients with sarcoidosis disease resolving within 2 years, i.e., good prognosis disease." (PMID 31921204, 2019). "HLA-DRB1*03+ RA patients tend to be anti-CCP seronegative and, reminiscent of HLA-DRB1*03+ sarcoidosis patients, have a better prognosis." (PMID 30038611, 2018). "This work used an original stratification based on the HLA haplotypes, those which may influence disease occurrence and progression (HLA-DRB1*03:01 and HLA-DRB1*04:01-DPB1*04:01), and a replication study in a large set of sarcoidosis patients and controls." (PMID 32823753, 2020). "In Finnish sarcoidosis patients, good prognosis subjects more commonly have HLA-DRB1*03:01 and/or HLA-DRB1*04:01-DPB1*04:01 haplotype, but no marker for persistent disease have been found." (PMID 31921204, 2019). "In sarcoidosis, significant differences in AVA production were observed between HLA-DRB1*03 positive and negative patients and not between LS and non-LS sarcoidosis patients (data not shown)." (PMID 30038611, 2018). "Both rs3177928 and rs6937545 are also cis-acting eQTL affecting the expression of HLA-DRB1 and are not in LD with other HLA-DRA gene variants previously associated with sarcoidosis." (PMID 28469621, 2017).
sarcoidosis (continued). "In familial cases, we have checked for SNPs within the HLA-DRB1/DPB1 genes in 9 unrelated index cases of familial sarcoidosis and found no common genotypes; this suggests that these index cases do not have a common ancestor and that there is no founder effect." (PMID 27914482, 2016).
systemic lupus erythematosus (52 papers, 2008 to 2026). An autoimmune multi-organ disease typically associated with vasculopathy and autoantibody production. "Regarding HLA-DRB1*08, this allele was positively associated with systemic lupus erythematosus (SLE) and systemic sclerosis (SSc)." (PMID 33327594, 2020). "Although it is difficult to define HLA-DRB1*1501 as a molecular biomarker of anti-GBM nephritis or lupus, the fact that these identical twins were both HLA-DRB1*1501 homozygotes supports the possible association of this allele with anti-GBM and lupus." (PMID 24359316, 2013). "However, HLA-DRB1*03:01 has been reported as a major risk factor for systemic lupus erythematosus and acts as a disease modifier for autoimmune hepatitis type 1." (PMID 41296809, 2025). "The lupus-associated variant in this SNP tags the lupus-associated classical alleles DRB1*03:01 and DRB1*15:01, and is associated with increased expression of HLA-DRB1, HLA-DQA1, and HLA-DQB1 in monocyte-derived dendritic cells." (PMID 35902632, 2022). "For example, although STAT1 mRNA levels are both increased in lupus and normal CD8+ T cells with IFN-α stimulation, the signature of hypomethylated DNA sites in lupus CD8+ T cells facilitates the upregulation of HLA-DRB1 in a STAT1-signaling-dependent manner." (PMID 34305954, 2021). "On this line, the MHC class II molecules HLA-DQB1 and HLA-DRB1, along with the MCH class I HLA-C, have been recently associated with resistance to systemic autoimmune diseases, such as systemic sclerosis, systemic lupus erythematosus and rheumatoid arthritis." (PMID 31511551, 2019). "Considering HLA-DRB1*1501 alleles are associated with susceptibility to anti-GBM nephritis and lupus, we analyzed HLA-DRB1 alleles in these two sisters, and they were both HLA-DRB1*1501 homozygotes." (PMID 24359316, 2013). "Furthermore, hypomethylation of HLA-DRB1 loci also induces HLA-DRB1 expression in systemic lupus erythematosus CD8+ T cells." (PMID 32370106, 2020). "Finally, the HLA-DRB1*03 allele, which also conferred increased risk of AAA formation, has been shown to be associated with autoantibody formation in lupus." (PMID 29614084, 2018). "We also demonstrate a putative predisposing effect of HLA-DR4 haplotypes in these diseases: HLA-DRB1*0401 (or a variant in LD with this allele) in non-European lupus cohorts and several different HLA-DRB1*04 alleles in MS." (PMID 18437207, 2008). "Systemic lupus erythematosus (SLE), a disease characterised with production of antibodies against self-antigens and consequently inflammatory events leading to the destruction of internal organs (kidney, heart, joints, brain, haemopoietic system), has been associated with HLADRB1* allele." (PMID 40557170, 2025). "Next-generation sequencing analysis of the MHC region (previously suggested to be a hot region in atypical psychosis) using HLA typing (HLA-DRB1) revealed a common vulnerability with SLE (systemic lupus erythematosus) among five patients." (PMID 30323194, 2018). "By KEGG pathway analysis, six genes, i.e., C4A, C4B, FCGR2A, HLA-DMA, HLA-DRA, and HLA-DRB1, were enriched as the top 2 significant results in the pathways of Staphylococcus aureus infection (KEGG term hsa05322, FDR = 1.42E−05) and systemic lupus erythematosus (KEGG term hsa05150, FDR = 2.00E−04)." (PMID 34804021, 2021). "An association study was conducted for HLA-DRB1, DQB1, and DPB1 in Japanese RA and systemic lupus erythematosus (SLE) patients that were positive or negative for anti-Ro/SS-A and/or anti-La/SS-B antibodies." (PMID 23320107, 2013).
diabetes (28 papers, 2010 to 2025). "They reported that 48% and 44.3% of pediatric patients with T1D had 2 and 1 HLA-DRB1 risk alleles, respectively, which was significantly greater than the proportion found in patients with monogenic diabetes and healthy controls." (PMID 39243072, 2024). "HLA-DRB1*03:01 (p = 0.0014) and HLA-DRB1*04 (p = 0.0001) were positively associated with this form of diabetes, while HLA-DRB1*15 was protective (p < 0.0001)." (PMID 32705316, 2020). "HLA-DRB1*03:01 was positively associated with diabetes (81/188, 43.1%) compared with control participants (40/152, 26.3%; OR 2.12; p = 0.0014), and this association persisted when considering only GADA-positive cases (54/102, 52.9%)." (PMID 32705316, 2020). "HLA-DRB1*04 was also positively associated with diabetes (83/188, 44.1%) vs control participants (37/152, 24.3%; OR 2.46; p = 0.0001); this association persisted when GADA-positive cases only were considered (51/102, 50.0%)." (PMID 32705316, 2020). "The association of the JM antibody response with HLA-DRB1*04, both in the period before and at the time of diabetes onset, in this study and other studies implicates immune responses to determinants within the JM domain as a potential contributor to diabetes susceptibility conferred by this allele." (PMID 26564179, 2016). "HLA-DRB1*15 was strongly protective in the total diabetes group (7/188, 3.7%) compared with control participants (25/152, 16.4%; OR 0.20; p < 0.0001); this association persisted when GADA-positive cases only were considered (2/102, 2.0%)." (PMID 32705316, 2020). "We would like to point out that it is the combination of HLA-DRB1, DQA1, and DQB1 alleles that determines the diabetes risk in our cohort." (PMID 28534863, 2017). "The first exon of HLA-DRB1 cannot be transcribed due to abnormal splicing, which may also affect the occurrence and development of diabetes." (PMID 36967753, 2023). "Peripheral blood RNA sequencing results of patients and carriers suggest that WFS1 may affect immune-related pathways and the transcriptional expression of HLA-DRB1 may be related to the pathogenesis of diabetes." (PMID 36967753, 2023). "Additionally, the expression of HLA-DRB1 is also predictive of type 2 diabetes, as is the expression of CIITA and another HLA-DRB1 TF, RFX5, which determine susceptibility to type 2 diabetes mellitus." (PMID 35627314, 2022). "We assessed their demographic and socioeconomic characteristics, and measured non-fasting C-peptide, diabetes-associated autoantibodies and HLA-DRB1 alleles." (PMID 32705316, 2020). "In addition, these Amhara diabetes patients showed an association with HLA class II alleles HLA-DRB1*03:01 and HLA-DRB1*04, in both the total diabetes cohort as well as in those with GADA, while HLA-DRB1*15 was strongly protective for diabetes." (PMID 32705316, 2020). "Therefore, the associated alpha-chain DQA1*05:01 or the associated HLA-DRB1*03:01, occurring in the linkage disequilibrium with DQB1*02:01, must be responsible for differences in diabetes risk." (PMID 28534863, 2017). "HLA-DRB1 genotyping together with all known biomarkers, could be helpful in order to select pediatric patients with high probability of monogenic diabetes." (PMID 28052112, 2017). "This association raises the hypothesis that the severity of periodontitis in these individuals may be influenced by a genetic predisposition conferred by the HLA-DRB1*15 haplogroup, independent of their diabetes status." (PMID 40283738, 2025). "However, although the HLA-DRB1*15 haplogroup is not directly associated with diabetes as a risk allele but as a protective allele, this study found it relevant in patients with diabetes and with severe and generalized periodontitis." (PMID 40283738, 2025). "The findings on the HLA-DRB1*03 and HLA-DRB1*15 haplogroups in the study patients are relevant when considering the relationship between severe and generalized periodontitis, systemic diseases (e.g., diabetes), and the ancestry of the individuals." (PMID 40283738, 2025).
diabetes (continued). "Our study found that the expression of the HLA-DRB1 transcriptome in the patient group was higher than that in the parent group without diabetes." (PMID 36967753, 2023). "Whether the abnormal expression or splicing of HLA-DRB1 was related to diabetes was not clear but deserves further attention and experimental investigation." (PMID 36967753, 2023).
asthma (25 papers, 2006 to 2026). "IRF1 (PPH4/PPH3 + PPH4 = 0.975), OXER1(PPH4/PPH3 + PPH4 = 0.967), PSMA4(PPH4/PPH3 + PPH4 = 0.972), UNC13D (PPH4/PPH3 + PPH4 = 0.989) and HLA‐DRB1(PPH4/PPH3 + PPH4 = 0.948) expression had significant colocalization associations with asthma." (PMID 41573111, 2026). "HLA‐DRB1: Explore peptide therapies or immunomodulators targeting specific HLA‐DRB1 alleles associated with asthma risk." (PMID 41573111, 2026). "For White participants, two MHC class I alleles, HLA-B*40:02 and HLA-C*04:01, and one MHC class II allele, HLA-DRB1*04:05, were significantly associated with late-onset asthma." (PMID 37415598, 2023). "In accordance with the HLA allele analysis results, within HLA-DRB1, the amino acid variants at positions 37 and 38 were significantly associated with late-onset asthma." (PMID 37415598, 2023). "At least two independent loci characterised by amino acid changes in the HLA-DQA1, HLA-DQB1 and HLA-DRB1 genes are likely to account for association of SNPs and CNVs in this region with asthma." (PMID 35597955, 2022). "Two significant pathway sets, i.e. asthma and intestinal immune network for IgA production, were detected in the cohorts carrying the HLA-DRB1*01-DQB1*05:01 risk haplotypes." (PMID 34976003, 2021). "HLA-DQB1*03 and HLA-DRB1*13 have also been associated with A. alternata moderate to severe asthma in children, where HLA-DQB1*03 was reduced in frequency and HLA-DRB1*13 increased in frequency when compared to A. alternata mild asthmatic children." (PMID 31824491, 2019). "In India and USA, studies showed a significantly higher frequency of HLA-DRB1*03 in asthmatics than in controls while in our study we found HLA-DRB1*03 is a protective allele against asthma." (PMID 30455876, 2018). "•To identify/compare the association between HLA-DRB1 alleles and development of asthma in a sample of Iraqi Arab Muslims." (PMID 30455876, 2018). "In our research, we investigated the association of HLA class II (HLA-DRB1) with asthma in Iraqi patients." (PMID 30455876, 2018). "HLA alleles have an effect on development asthma in patients with HLA-DRB1*070101 while HLADRB1* 030101 is a protective allele in Iraqi Arab Muslims individuals against development of asthma." (PMID 30455876, 2018). "The association between asthma and the HLA-DRB1 locus has been identified in a family-based population sample." (PMID 29378629, 2018). "The allele frequency of HLA-DRB1*13 tended to be increased in Alternaria-sensitive moderate-severe asthma compared to Alternaria-sensitive mild asthma, 37% versus 20% (p = 0.06)." (PMID 20298583, 2010). "•HLA alleles have an effect on development asthma in patients with HLA-DRB1*070101 while HLADRB1* 030101 may have a protective effect." (PMID 30455876, 2018). "In conclusion, it is suggested that HLADRB1*0701 and HLADRB1*0301 alleles might be the possible genetic factors for susceptibility and protection against asthma respectively." (PMID 30455876, 2018). "Five druggable genes significantly associated with asthma were identified in whole blood (IRF1, OXER1, PSMA4, UNC13D, and HLA‐DRB1) and one in lung tissue (CD226)." (PMID 41573111, 2026). "For Black participants, two MHC class II alleles, HLA-DRB1*03:01 and HLA-DQB1*02:01, were significantly associated with increased risk of being a late-onset asthma case [(OR = 4.00, 95%CI: 1.46 to 10.91; OR = 2.25, 95%CI: 1.09 to 4.65), respectively]." (PMID 37415598, 2023). "For Black participants, the HLA-DRB1*03:01 and HLA-DQB1*02:01 alleles were significantly associated with late-onset asthma." (PMID 37415598, 2023). "HLA-C*04:01 was protective for being a late-onset asthma case (OR = 0.25, 95%CI: 0.09 to 0.70) whereas HLA-B*40:02 and HLA-DRB1*04:05 increased the odds of being a case [(OR = 3.77, 95%CI: 1.91 to 7.44; OR = 8.19, 95%CI: 2.51 to 26.79), respectively]." (PMID 37415598, 2023).
asthma (continued). "In the second place, studies have pointed out that asthma and RA may have overlapping genetic predispositions, and certain genetic variants in immune-related genes are associated with increased susceptibility to asthma and RA, such as HLA-DRB1, CD40L, and CD86." (PMID 36869337, 2023). "For the HLA analysis, HLA-B*40:02 and HLA-DRB1*04:05, HLA-B*40:02, HLA-C*04:01, and HLA-DRB1*04:05, and HLA-DRB1*03:01 and HLA-DQB1 were significantly associated with late-onset asthma in all, White, and Black participants." (PMID 37415598, 2023). "Fine-mapping the HLA region suggested that there are at least two asthma association signals in this region and that amino acid changes in HLA-DQA1, HLA-DQB1 and HLA-DRB1 genes are most likely to be the underlying causal variations." (PMID 35597955, 2022). "As for genetics, HLA-DRB1 and HLA-DQB1 genes were independently associated with asthma and its related traits in numerous candidate gene association studies, and HLA-DRB1 was found to be the major determinant of the association with RA susceptibility." (PMID 29849649, 2018). "This study evaluated 8 of these genes (IL4, IL13, TNF-α, HLA-DRB1, HLA-DQB1, FCER1B/MS4A2, CD14, ADAM33) as well as 3 glutathione-s-transferase genes (GSTM1, GSTP1, and GSTT1) for association with asthma/allergy among urban-residing African Americans." (PMID 21320344, 2011). "Fine-mapping of imputed HLA variation and putative CNVs demonstrated that there are likely to be at least two real, independent, association signals for asthma within the HLA region, one involving primarily HLA-DQA1 and HLA-DQB1 variation and one involving primarily HLA-DRB1 variation." (PMID 35597955, 2022). "Finally, transcriptomic data from bronchial brushing and bronchoalveolar lavage (BAL) samples revealed that HLA-DQA1 (only available for bronchial brushing), HLA-DQB1, and HLA-DRB1 were downregulated in patients with severe asthma compared to healthy controls." (PMID 34880287, 2021). "Furthermore, the well-reported asthma-associated genes of HLA-DQA1, HLA-DRB1, and HLA-DRB5 have the most number of interacted edges with identified and predicted genes." (PMID 33066754, 2020). "HLA alleles have an effect on development asthma in patients with HLA-DRB1*070101 while HLADRB1* 030101 may have a protective effect in Iraqi Arab Muslims individuals against development of asthma." (PMID 30455876, 2018). "Additionally, the identified childhood-onset asthma-associated gene of JAZF1 has evidence of genetic interactions with identified genes of AHI1, NSMCE1, TDRKH, CD52, and HLA-DRB1 based on a genome-wide map of genetic interaction inferred from radiation hybrid genotypes." (PMID 32867763, 2020). "A recent single-cell RNA sequencing analysis found that pediatric patients with HDM-sensitized asthma displayed increased expression of the HLA-DRA and HLA-DRB1 genes in their PBMCs." (PMID 41462706, 2025). "Gene expression levels of the HLA-DRA (1.01 ± 0.43 versus 0.67 ± 0.23-fold change, adjusted p = 0.019) and HLA-DRB1 (1.42 ± 0.74 versus 0.81 ± 0.36-fold change, adjusted p = 0.011) genes were both elevated in the COPD-only group compared to the asthma-only group." (PMID 41462706, 2025). "The CCL5 -471C>T SNP, which we found might be associated with MS in HLA-DRB1*1501 negative patients, is of potential functional relevance, as it creates a new transcription factor binding site, and has shown associations with atopic dermatitis, atopy and asthma." (PMID 16872505, 2006).